BTBD8 (BTB domain containing 8)
Description:
Involved in clathrin-mediated endocytosis at the synapse. Plays a role in neuronal development and in synaptic vesicle recycling in mature neurons, a process required for normal synaptic transmission.
Synonyms: APache; KIAA1107
Tractability: No criterion of Open Targets' tractability assessment is met for any kind of drug.
Gene: Protein-coding gene on chromosome 1 (92,080,305 to 92,184,725, forward strand). Ensembl gene ENSG00000189195.
Subcellular location: Cell projection, axon; Presynapse; Cytoplasmic vesicle, clathrin-coated vesicle; Nucleus
Subcellular location (Human Protein Atlas): Nucleoplasm
Gene Ontology:
Biological process: synaptic vesicle budding from endosome; synaptic vesicle endocytosis
Cellular component: nucleoplasm; nucleus; AP-2 adaptor complex; axon; clathrin-coated vesicle; extrinsic component of synaptic vesicle membrane; neuron projection terminus; presynapse; synaptic vesicle
Genetic constraint (gnomAD): Loss-of-function variants: 84 observed, 133.78 expected, observed/expected ratio (o/e) 0.63, 90% interval 0.52 to 0.75. The upper end of that interval is the gene's LOEUF score, 0.75, which puts it in group 3 of 6, group 1 being the genes least tolerant of losing a copy. Missense variants: 1,775 observed, 2,017.1 expected, observed/expected ratio (o/e) 0.88, 90% interval 0.85 to 0.92. Synonymous variants: 630 observed, 702.79 expected, observed/expected ratio (o/e) 0.9, 90% interval 0.84 to 0.96.
Homologues: Orthologues: macaque BTBD8 (92% identical), rabbit BTBD8 (80% identical), dog BTBD8 (79% identical), chimpanzee KIAA1107 (78% identical), pig BTBD8 (74% identical), mouse Btbd8 (65% identical), rat Btbd8 (63% identical), guinea pig BTBD8 (61% identical), tropical clawed frog btbd8 (39% identical). Paralogues in human: PRR36 (11% identical).
Diseases named in the same sentence as BTBD8 in open-access papers:
BTBD8 is named in the same sentence as 21 diseases in open-access papers, as found by Europe PMC text mining. Sharing a sentence is not in itself a finding about the gene and the disease. The quoted sentences say what the papers report.
colitis (1 paper, 2024). Inflammation of the colon. "The reduced susceptibility to DSS-induced colitis in Btbd8 KO mice may attribute to enhanced intestinal barrier function and suppressed inflammation." (PMID 38558797, 2024). "Next, we attempted to address whether Btbd8 deficiency affects the development of colitis." (PMID 38558797, 2024). "To induce IBD, we administered 3% DSS in drinking water to both wild-type (WT) and Btbd8 KO mice for 7 days, and monitored colitis symptoms in these mice." (PMID 38558797, 2024). "DSS induced colitis symptoms are more severe in WT mice than in Btbd8 KO mice, which might result in more impaired intestinal barrier in DSS treated WT mice." (PMID 38558797, 2024). "To avoid the intestinal barrier damage caused by colitis, we assessed the intestinal barrier integrity in untreated mice or mice treated with DSS for 2.5 days, in which no colitis symptom difference between WT and Btbd8 KO mice, including colonic length and histopathology, was observed." (PMID 38558797, 2024).
inflammatory bowel disease (1 paper, 2024). A spectrum of small and large bowel inflammatory diseases of unknown etiology. "BTBD8 has been identified as a susceptible gene for inflammatory bowel diseases (IBD)." (PMID 38558797, 2024).
meningioma (1 paper, 2023). A generally slow growing tumor attached to the dura mater. "In the study, miR-3605-5p, miR-664b-5p, PNRC2, BTBD8, SLFN13, DGKD, NSD2, EXTL2, and BVES were closely corrected with the malignant progression of meningioma." (PMID 37024523, 2023).
BTBD8 also shares sentences with these, for which no sentence is quoted: Sepsis (17 papers); pneumonia (3); cancer (2); chronic heart failure (2); COVID-19 (2); diabetes (2); infection (2); acute abdomen (1); acute pancreatitis (1); acute respiratory failure (1); breast carcinoma (1); Cirrhosis (1); dementia (1); frontotemporal lobar degeneration (1); immune dysfunction (1); multiple sclerosis (1); scabies (1); septic shock (1).